FOXM1 (forkhead box M1)
Diseases named in the same sentence as FOXM1 in open-access papers (continued):
Sharing a sentence is not in itself a finding about the gene and the disease.
cancer (continued). "Similar to common cancer cells, multiple abnormal signaling pathways are found in PCSCs, such as Hedgehog (HH), Notch, Wnt, Bmi, PI3K/AKT/PTEN, FOXM1, and Nodal/Activin." (PMID 24325450, 2013). "FoxM1 and STAT3 are often related to cancer and present similar consequences when overexpressed or inhibited." (PMID 23110199, 2012). "The complexity of genomic instability and epigenetic reprograming activated by FOXM1 may therefore generate a highly heterogeneous population of mutant cells ready to adopt subsequent oncogenic insults which may explain the heterogeneity exists in many cancers." (PMID 23087907, 2012). "Collectively, the FoxM1 gene is aberrantly activated in AML and is required for sustained proliferation of the cancer cells." (PMID 22900969, 2012). "Foxm1 transcription factor (also known as HFH-11B, Trident, Win or MPP2) plays an important role in the pathogenesis of various cancers and is a critical mediator of post-injury repair in multiple organs." (PMID 23144938, 2012). "However, specific requirements for the Foxm1 in each cell type of the cancer lesion remain unknown." (PMID 19672312, 2009). "The gene expression changes in model cells aligned with gene expression changes observed in aneuploid cancers and uncovered the transcriptional factors E2F4 and FOXM1 to critically contribute to adaptation to chromosome gains, which we experimentally validated." (PMID 39930267, 2025). "We analyzed expression levels and intracellular localization of seven common cancer antigens, CLDN1, EphB4, LAT1, FOXM1, HSP105α, ROBO1, and SPARC, and human leukocyte antigen (HLA) class I via immunohistochemical staining of 85 surgical specimens from primaries and liver metastases." (PMID 40806530, 2025). "The blunt inhibition of FOXM1, without devices able to target it specifically towards cancer cells, would have detrimental effects on the overall health of the treated patient, much like standard untargeted chemotherapy." (PMID 39858603, 2025). "FOXM1 is generally a negative predictor of survival, with significantly negative prognostic power in four cancer types." (PMID 39858603, 2025). "Moreover, we found FOXM1 inhibition enhanced T cell activation and supported the differentiation of CD8 + cytotoxic T cells, and T cell-mediated killing of cancer cells." (PMID 40630538, 2025). "In cancer, this same PI3K/AKT axis plays a pivotal role in driving FOXM1 activity." (PMID 40501685, 2025). "The expression level of DNMT1 showed an inverse correlation with that of miR-34a-5p, while it exhibited a positive correlation with the level of FoxM1, and high DNMT1 levels, low miR-34a-5p levels, and high FoxM1 levels were correlated with cancer recurrence in the HCC patients." (PMID 40050970, 2025). "The data presented here show that, in addition to FOXM1, targeting AURKB and PLK1 may curb the increased cell proliferative activity of cancer cells." (PMID 40149290, 2025). "Remarkably, the mere activation of Wnt/ERK/CDK4/6 in E/M cells suffices to cement a programme integrating cancer stem cell maintenance (via FOXC2/p63) and self-renewal (via S-phase and FOXM1 activation) with inhibition of differentiation (via EGFR inactivation)." (PMID 40764669, 2025). "The cancer-promoting transcription factor FOXM1 is greatly increased in many cancers and is absent in most normal adult tissues." (PMID 38980505, 2024). "Among the top-ranked factors, we were particularly interested in FOXM1, a gene with important roles in other cancer types but that has not been extensively characterized in EAC." (PMID 38373993, 2024). "Considering FOXM1 as a critical regulator of sensitivity and resistance in human cancers, we assumed that STL001 treatment-induced FOXM1 suppression should reduce chemoresistance and sensitize human cancer cells to the cytotoxic effects of the relevant cancer chemotherapies." (PMID 38697979, 2024).
cancer (continued). "Understanding the dynamic between FOXM1 and FHRE within the KIF20A promoter could pave the way for novel cancer treatment modalities, particularly where the dysregulation of KIF20A contributes to disease progression." (PMID 39272816, 2024). "Moreover, FOXM1-PROTAC inhibits the proliferation, migration, and invasion of cancer cells, including in in vitro HepG2 and MDA-MB-231 models." (PMID 39594778, 2024). "Forkhead box M1 (FOXM1) is a member of the conserved forkhead box (FOX) transcription factor family, recognized for its role as a multifunctional oncoprotein regulating the expression of numerous cancer-promoting genes." (PMID 39077467, 2024). "The mechanisms of action of these agents against FOXM1, and their anti-cancer activities have not been studied extensively." (PMID 38704607, 2024). "In contrast to FOXM1, FOXO3 is regarded as a tumor suppressor and the overexpression of FOXO3 can inhibit the proliferation, tumorigenic potential and invasiveness of various cancer cells." (PMID 38725864, 2024). "Furthermore, FOXM1 is commonly expressed in recurrent chemoresistant EOC and targeting FOXM1 using SMIs shows anti-cancer effects in EOC cells." (PMID 38791105, 2024). "Forkhead box M1 (FOXM1) is a member of the Forkhead box (Fox) protein family characterized by a master regulator of cell survival, self-renewal, and tumorigenesis in various cancer cells." (PMID 38978058, 2024). "Therefore, we overexpressed PTPN13 expression to counteract the cancer‐promoting effects of the overexpressed METTL1 and FOXM1." (PMID 38967523, 2024). "Notably, tumors with elevated FOXM1 share many features with MPNSTs that are resistant to CDK4/6-MEK inhibition, most of which reflect extra-tumoral changes that suppress anti-cancer immunity." (PMID 39347707, 2024). "FOXM1 acts as a transcriptional regulator of promoting cell cycle advancement, while GLUT1 serves as a carrier for glucose uptake viaglycolysis, particularly in tumors and often connected to cancer phenotypes." (PMID 38611849, 2024). "We present these perspectives and future directions in the context of what is known about FOXM1, its regulation, and its key roles in promoting cancer aggressiveness and metastasis, while being absent or very low in most normal non-regenerating adult tissues." (PMID 37370117, 2023). "Thus, our results provide the basic evidence that HMGA1 and FOXM1 cooperatively accelerate cell cycle progression by up-regulating PLK1 and CCNB1 to promote cancer cell proliferation." (PMID 37240870, 2023). "After filtering through TCGA and the Cancer Imaging Archive (TCIA) database, we employed dual-region computed tomography (CT) radiomics technology to noninvasively predict the mRNA expression of FOXM1 in HCC tissues." (PMID 37817774, 2023). "Together with the observation that RvD inhibits FOXM1 expression in CAFs and represses EMT and cancer stemness, a potential role of resolving lipids in regulating cancer stemness through PTEN-PI3K signaling maybe proposed." (PMID 36818443, 2023). "Currently, there are no commercially available anti-cancer therapeutics specifically targeting FOXM1." (PMID 37598210, 2023). "In addition, studies indicates that FOXM1 has an oncogenic role in AML and can contribute to the development of drug resistance in cancers." (PMID 37526082, 2023). "Despite the well-known roles of FOXM1 in cancer, there has been a lack of investigation of FOXM1 in RMS." (PMID 36816948, 2023). "It is noteworthy that FOXM1 showed elevated expression in all 16 cancer types, including 15 cancers with statistical significance and 1 cancer (THCA) without significance." (PMID 37401400, 2023).
cancer (continued). "Notably, FOXM1B and FOXM1C isoforms, which are transcriptional activators, were responsible for FOXM1 upregulation in cancer according to a recent study." (PMID 38001498, 2023). "While its role in this disease has not been sufficiently investigated, it is well known that FOXM1 is required for the proliferation, survival, and metastasis of many other cancer types." (PMID 37686402, 2023). "Furthermore, it was previously been reported that FOXM1 overexpression is related to the presence of the progressive TNM stage and metastasis lymph node, suggesting that FOXM1 is possibly involved in cancer metastasis and invasion." (PMID 35845311, 2022). "Therefore, an anti‐cancer drug with FOXM1 protein peptides coupled with CPP can be designed to make therapeutic proteins enter cancer cells and play an anti‐cancer role." (PMID 35593206, 2022). "The results show that FOXM1-PROTAC had a more potent inhibitory effect on cancer cell viability than peptide FIP-1, which is expected as FIP-1 inhibits FOXM1 only by binding to FOXM1, whereas FOXM1-PROTAC eliminates the majority of FOXM1 and can bind to the remaining nondegraded FOXM1." (PMID 36171633, 2022). "Indeed, the upregulation of CENP-A strongly correlates with the expression of FOXM1 across many cancers and FOXM1 displays at least 100-fold relative enrichment at the CENPA promoter in cancer tissues compared with normal tissues." (PMID 35721491, 2022). "Furthermore, there are significant correlations between FOXM1 expression and the infiltrating levels of different types of immune cells, TMB, MSI and immune checkpoint genes in a variety of cancers." (PMID 36435510, 2022). "In OSCC cancer cells, correlations between DEPDC1 and FOXM1 were also discovered." (PMID 36072787, 2022). "Transcriptionally, LDHA is regulated by forkhead box protein M1 (FOXM1), hypoxia-inducible factors (HIF-1α and HIF-2α), Jumonji C Domain 2A (JMJD2A), and peroxisome proliferator-activated receptor gamma (PPAR-γ) coactivator 1-beta (PGC1β) in cancer cells." (PMID 35832094, 2022). "A positive correlation was found between FOXM1 and TMB in 19 cancer types." (PMID 36435510, 2022). "Given that FOXM1 is an established therapeutic target for several cancers, the identification of a compound that inhibits FOXM1- and FFOXM1-mediated DNA repair has important translational potential for treating many aggressive cancers." (PMID 35805019, 2022). "Saleembhasha and Mishra 32, first published in 2017 working with a TCGA RNA-seq dataset of 5601 samples from 15 different primary cancer types, proposed a pan-cancer regulatory axis consisting of PVT1, E2F1 and FOXM1 as common gene expression regulatory entity." (PMID 35534592, 2022). "Since CDI did not report any anti-cancer effect, it was decided to analyze the inhibitory effect on FoxM1-DBD." (PMID 35884976, 2022). "The forkhead box protein M1 (FOXM1) is a member of the FOX transcription factor family and plays an important role in the regulation of cell-cycle progression, drug resistance, CSC renewal, and cancer differentiation." (PMID 35887129, 2022). "The impact of OxA treatment on chemoresistant tumors, on the expression of various proteins such as Nrf2, p-eIF2α, ATF4, PolQ, FoxM1, and Bcl2, which are involved in cancer chemoresistance, is not shown." (PMID 35747788, 2022). "Furthermore, patients with high levels of FOXM1 and LMNB1 have poor survival, consistent with faster cancer growth." (PMID 35719698, 2022). "FOXM1 and RHNO1 are one of the first examples of oncogenic BDG, and therapeutic targeting of FOXM1/RHNO1 BDG is a potential therapeutic approach for ovarian and other cancers." (PMID 33890574, 2021).
cancer (continued). "To evaluate whether FOXM1 is a valuable target, we analyzed the differential expression of FOXM1, PARP1, and PARP2 between cancer tissues and adjacent normal tissues in 31 cancers from the TCGA projects." (PMID 34880209, 2021). "Overall, this conceptual framework may prove useful to guide future studies of FOXM1 and RHNO1 and their interplay in normal physiology and cancer." (PMID 33890574, 2021). "Since FoxM1 and STMN1 both play important roles in the process of cell cycle regulation, we wondered to know whether there is a functional link in cancers." (PMID 33526768, 2021). "The epigenetic signature induced by FOXM1 has been speculated to possess the clinical translational potential to function as a biomarker for HNSCC, including early cancer screening, diagnosis, and therapy, as it can mimic the cancer epigenome." (PMID 34447693, 2021). "However, the present study demonstrates that individual targeting of either FOXM1 or RHNO1, using shRNA or CRISPR-Cas9, significantly reduces HGSC cell clonogenic growth, suggesting that each protein contributes to cancer phenotypes." (PMID 33890574, 2021). "In this subtype, FOXM1, TOP2A, CCNB1, CCNB2, and CDC25A participate in DNA repair and are activated during disease relapse or play a role in the prognosis of other cancers, thereby supporting the poor prognostic characteristics of the DP.BCG+ subtype." (PMID 33535616, 2021). "Meanwhile, the expression of FOXM1 is also regulated by oncogenic Ras-mediated ROS generation, and elevated FOXM controls the oxidative stress balance to accelerate the growth and survival of cancer cells." (PMID 34740322, 2021). "FOXM1 and PARP1 were generally overexpressed in various cancer tissues." (PMID 34880209, 2021). "Moreover, FOXM1 showed greater overexpression in tumor tissues compared to RHNO1, and, consistently, the FOXM1/RHNO1 expression ratio was elevated in cancer." (PMID 33890574, 2021). "In cancer cells, this appears under the control of a particular gene from the FOXO family, FOXM1." (PMID 33867999, 2021). "To figure out whether there is a general correlation between FoxM1 and STMN1 in cancers, we then analyzed the expression patterns of them." (PMID 33526768, 2021). "In addition, the correlation between FOXM1 and RNF26 in the cancer patient samples was analyzed through the GEPIA web tool." (PMID 34650035, 2021). "FoxM1 regulates prohibitin 1 (PHB1) at the transcription and translation levels, which promotes activation of RAF‐MEK‐ERK signaling, leading to the phosphorylation of ERK1/2 to support the continuous proliferation of cancer cells." (PMID 34766149, 2021). "The molecular mechanisms contributing to high FOXM1 levels in cancer, including AML, are still not completely understood." (PMID 34381718, 2021). "Based on these data, we hypothesize that the FOXM1/RHNO1 BDG pair promotes HGSC and other cancers, and is a potential target for cancer therapeutic intervention." (PMID 33890574, 2021). "While FOXM1 is overexpressed in HGSC and pan-cancer, RHNO1 expression in normal tissues vs. cancer is unknown." (PMID 33890574, 2021). "Another transcription factor, forkhead box protein M1 (FOXM1), which is vital for cell proliferation, cell cycle progression, tissue homeostasis, and DNA damage repair, has been shown to regulate metastasis in different cancers." (PMID 32899427, 2020). "On the other hand, in the ERα-negative cancer cell line, FOXM1 binds mainly to the motifs of other transcription factors, such as leucine zippers and c-MYC, but not to ERα." (PMID 32858881, 2020). "Expression of CENPA, FOXM1, and MYBL2 did not appear to be very strongly associated with age, sex, or cancer stage." (PMID 32925947, 2020). "The results indicated that FOXM1 and PLAU are overexpressed in 17 cancer types including GC." (PMID 31949481, 2020).
cancer (continued). "Tumor samples with higher expression of CENPA, FOXM1, and MYBL2 appear to harbor relatively more cancer-specific enhancers, suggesting that tumors highly expressing CENPA, FOXM1, and MYBL2 may have distinct enhancer profiles." (PMID 32925947, 2020). "Because 4SC-202 affects the cell population(s) that express CD133, FOXM1, and SOX2 and there is strong evidence that these proteins are cancer stem cell markers, our data suggest that 4SC-202 may decrease the cancer stem-like cell population." (PMID 32210076, 2020). "In addition, we also found significant positive correlations of gene expressions between FOXM1 and the NFY subunits (NFYA, NFYB or NFYC) in several cancer types." (PMID 32858881, 2020). "We analyzed FOXM1 and PLAU mRNA expression in different cancer types using TIMER52." (PMID 31949481, 2020). "Given that our results show that radiation and FOXM1 induce replication stress, a known driver of cancer initiation and progression, we tested next whether exposure to radiation promotes cell transformation in HBEC3-KT and involves FOXM1 in this process." (PMID 33253193, 2020). "Therefore, further experiments regarding the interaction between FOXM1 and the NFY complex are needed to demonstrate a key axis that can mitigate deregulated cell cycle-related pathways observed in various cancers." (PMID 32858881, 2020). "FOXM1 is known to be another gene relevant to the progression of HCC and other forms of cancer." (PMID 31777593, 2019). "The key findings are that through E2F1, FOXM1 and PVT1 regulatory axis and possible interactions with different coding genes, PVT1 may be playing a prominent role in pan-cancer development and progression." (PMID 30809433, 2019). "Similarly, in gastric carcinoma (GC) LDHA overexpression is transcriptionally regulated by FOXM1; overexpressed LDHA resulted in a glycolytic phenotype of cancer cells and promoted GC progression." (PMID 31146503, 2019). "Several other regulators showing differential activation pattern among DD and LS genes are involved in cell proliferation and cancer, e.g., KRAS [z-score = 2.14, -log(p-value) = 3.15] predicted to be activated in DD, or FOXM1 inhibited in LS [z-score = -3.24, -log(p-value) = 2.98]." (PMID 31249595, 2019). "FOXM1 is a transcription factor involved in the execution of the mitotic program and is overexpressed in proliferating cancer cells but not in quiescent ones as well as in terminally differentiated cells." (PMID 31234353, 2019). "Previous studies have revealed that FOXM1 expression is driven primarily by the Hedgehog, Ras/MEK/MAPK, signal transducer and activator of transcription 3 (STAT3), and wnt/β-catenin in different cancer cells." (PMID 30782607, 2019). "In this study, we postulated that RvD1 could inhibit COMP secretion in CAFs in a paracrine manner via FPR2/ROS/FOXM1 signaling to block stoma-tumor cells interactions and then suppress EMT and cancer stemness to alleviate malignant progression of HCC." (PMID 30999932, 2019). "In HCT-15 cells, reduced transcription of cell cycle mediating genes (CCND1, PCNA, CDK2, CDKN1B), and reduced transcription of anti-apoptotic genes (BMI1, BIRC5 and BCL2), support a cancer suppressive and favorable FOXO3/FOXM1 ratio upon combined TNKSi/MEKi treatment." (PMID 30717152, 2019). "FOXM1 is frequently overexpressed in cancer, but this has not been studied in a comprehensive manner." (PMID 30795624, 2019). "Furthermore, predicted activation of FOXO3 and inhibition of FOXM1 provides a positive FOXO3/FOXM1 ratio which is considered to be favorable, since these factors are crucial in various aspects of cancer progression." (PMID 30717152, 2019). "Since the target genes analyzed are key factors of several cancer hallmarks such as EMT, migration and angiogenesis, we next considered the possibility that HMGA1 and FOXM1 could act in concert in mediating cancer-related cell abilities." (PMID 31311575, 2019).